BRCA1 (BRCA1 DNA repair associated)
Diseases named in the same sentence as BRCA1 in open-access papers (continued):
Sharing a sentence is not in itself a finding about the gene and the disease.
breast cancer (continued). "According to the document research, BRCA1/2 genetic mutation exists in more than 80% of patients with high genetic breast cancer, and the incidences of lifetime breast cancer and breast cancer with this genetic mutation are much higher than the general population." (PMID 36172325, 2022). "Lifetime breast cancer risk is up to 1.2% in male BRCA1 carriers and up to 8.8% in BRCA2 carriers, compared to 0.1% in the general population; the lifetime prostate cancer risk is higher in BRCA2 than BRCA1 carriers and the general population, specifically up to 20–25%." (PMID 35448177, 2022). "BRCA1 or BRCA2 mutation also affects the treatment regimens for breast cancer." (PMID 36518309, 2022). "Furthermore, once transduced by single guide RNAs (sgRNAs) targeting Shld1 and Shld2, breast cancer cells with BRCA1 deficiency showed a diminished response to PARPi, similar to the results of in vivo experiments." (PMID 36253861, 2022). "Indeed, BRCA1-deficient breast cancers are positive for CK14, which seems to be associated with the development of triple-negative breast cancer." (PMID 36380314, 2022). "Pearson’s correlation and Spearman’s correlation analyses were performed for the three groups of breast cancer patients, i.e., BRCA1-mutated, BRCA2-mutated, and ErbB2-amplified breast cancer patients, depending on the normal or non-normal distribution of expression data." (PMID 35740092, 2022). "The effect of the BRCA1 L1780P mutation on breast cancer cell invasion and migration is consistent with that of other deleterious nonsense or frameshift mutations in BRCA1, suggesting that the BRCA1 L1780P mutation directly promotes TNBC cell invasion and metastasis." (PMID 35626017, 2022). "Although this effect is often attributed to heritable mutations such as BRCA1/2, the relationship between pathologic features, young age of onset, and prognosis for breast cancer remains unclear." (PMID 36304424, 2022). "Furthermore, we found that the expression of USP30-AS1 and C9orf163 were associated with BRCA1/2 status, indicating that they were involved in breast cancer development." (PMID 36276952, 2022). "This translates to a reduction in ovarian cancer-specific mortality between 80–96% and in breast cancer-specific mortality of 42%, which is more pronounced for BRCA1 (HR 0.45, p < 0.0001) vs. BRCA2 mutation carriers for whom the reduction loses significance (HR 0.88, p = 0.75)." (PMID 35267543, 2022). "The relative risk for breast cancer and ovarian cancer is 5.9 (95% confidence interval (CI): 5.3–6.7) and 11.8 (95% CI: 10.0–14.0) for BRCA1 mutant carriers, respectively, and 3.3 (95% CI: 3.0–3.7) and 5.3 (95% CI: 4.4–6.3) for BRCA2 mutant carriers, respectively." (PMID 35163129, 2022). "Moreover, TNBC is indicated as a type of breast cancer that has an aggressive clinical behavior, a high rate of proliferation, and a poor prognosis, as well as a mutation in the breast cancer gene 1 (BRCA1)." (PMID 35744786, 2022). "So, the mutation in BRCA1 also plays a causative role in the etiopathogenesis of breast cancer." (PMID 35163783, 2022). "Mutations in BRCA1 affect the proteins produced, resulting in an increased risk of breast cancer." (PMID 35200355, 2022). "Poly(adenosine diphosphate-ribose) polymerase inhibitors are approved to treat patients harboring a germline breast cancer susceptibility gene 1 or 2 mutation (BRCA1/2mut) with human epidermal growth factor receptor 2—negative (HER2−) advanced breast cancer (ABC)." (PMID 36358816, 2022). "Several studies also indicated that human patients with BRCA1-deficient breast cancer experienced more frequent locoregional recurrence and multiple-organ metastasis, especially in the lung and distant lymph nodes, than patients with sporadic breast cancers." (PMID 35025764, 2022).
breast cancer (continued). "In BRCA1-deficient cells, mTORC2 is overactivated, so BRCA1-deficient breast cancer cells may be dependent on mTORC2 signaling and more sensitive to its inhibition, further suggesting that mTOR plays a role in driving DNA damage events in tumor cells." (PMID 36147481, 2022). "In this study, it was found that 149 women (18.4%) developed contralateral breast cancer and that the risk of development considering a period of 15 years after diagnosis was 36.1% for carriers of mutations in the BRCA1 gene and 28.5% for women with BRCA2 gene mutations." (PMID 35805026, 2022). "In addition to this, cyclin-dependent kinase-12 inhibitors have reversed de novo and developed PARP inhibitor resistance in breast cancer cells mutated due to the BRCA1 gene." (PMID 35873570, 2022). "Women with BRCA1 or 2 gene deficiency are more likely to develop breast cancer." (PMID 36380314, 2022). "In addition, the NICE guidelines state that only for women with BRCA1 mutations, the opposing effects of potentially increased risk of breast cancer versus lifetime protection against ovarian cancer by taking OC should be discussed." (PMID 36230512, 2022). "The region of human chromosome 17q12-21, which contains the breast-cancer susceptibility gene known as BRCA1, is responsible for approximately 80% of breast-cancer families and ovarian cancer and is also associated with other types of cancer, such as pancreatic and colon cancers." (PMID 35200355, 2022). "Indeed, approximately 40% of inherited cancers are due to mutations in the breast cancer susceptibility genes 1 and 2 (BRCA1 and BRCA2)." (PMID 35406503, 2022). "Two-thirds (67%) of studies focused on cancer, and slightly more than one-third (38%) focused on just two types of commonly used tests (22% of studies focused on gene expression profiling tests for breast cancer and 16% on BRCA1/2 tests for breast cancer risk)." (PMID 35455673, 2022). "Indeed, PARP1 inhibitors are currently one of the most promising therapeutic agents for several cancers, especially breast cancer, and can selectively target tumor cells with BRCA1 or BRCA2 tumor suppressor gene mutations through synthetic lethality." (PMID 36266635, 2022). "BRCA1 (Breast Cancer 1, early onset) is linked to breast and ovarian cancer predisposition." (PMID 36171434, 2022). "The occurrence of mutations in BRCA1 gene is a risk factor for the development of breast cancer." (PMID 34643844, 2022). "Interestingly, for BRCA1 mutation carriers, breast cancer risk decreases after menopause when their sex hormones become substantially low." (PMID 35418083, 2022). "The findings reveal a biological foundation for increased risk of BRCA1-associated breast cancer." (PMID 35393420, 2022). "The lifetime risk for breast cancer in the BRCA1 male carrier is just over 1%." (PMID 35454911, 2022). "Additionally, heterozygous mutation of Brip1 predisposes to early onset breast cancer supporting its role in hereditary breast cancer development and BRCA1-related DNA repair mechanisms." (PMID 35105904, 2022). "However, an independent study has associated skewed XCI with advanced age at ovarian and breast cancer diagnosis among BRCA1 mutation carriers." (PMID 35456502, 2022). "Together, these observations corroborate the hypothesis that PTEN loss, which is highly associated with BRCA1-defective breast cancer, contributes to PARPi sensitivity." (PMID 35681784, 2022). "Inherited mutations in the BRCA1 and 2 genes lead to a serious increased risk of breast cancer." (PMID 35458452, 2022). "This lack of diversity in trials to test targeted therapies has important implications for breast cancer disparities given the marked variation in the prevalence of certain mutations of high-penetrance genes, such as BRCA1 and BRCA2, and breast tumor subtypes across racial and ethnic populations." (PMID 35151316, 2022).
breast cancer (continued). "Putative duplications overlapping the breast cancer tumour suppressor gene STK11 suggested decreased risk of breast cancer in our study for both BRCA1 carriers (HR = 0.49, 95%CI 0.29–0.81, p = 5.4 × 10−3) and BRCA2 carriers (HR = 0.44, 95%CI 0.22–0.88, p = 9.2 × 10−3)." (PMID 36203093, 2022). "Mutations in BRCA1 have been widely associated with the development of breast cancer." (PMID 36004205, 2022). "In approximately 70 and 23% of breast cancers, BRCA1 and BRCA2 mutations have been reported." (PMID 35145999, 2022). "Thus, these mammary tumor models allow for the evaluation of cancer prevention strategies, especially targeted toward Brca1 mutation carriers." (PMID 36333737, 2022). "Breast cancer is the most common neoplasia in females worldwide, about 10% being hereditary/familial and due to DNA variants in cancer-predisposing genes, such as the highly penetrant BRCA1/BRCA2 genes." (PMID 36035419, 2022). "Collectively, our study provided lists of candidate neoantigens that may be used to develop off-the-shelf cancer vaccines for BRCA1-related breast cancer patients or as a preventive cancer vaccine in BRCA1-mutated carriers." (PMID 36298462, 2022). "To investigate whether BRCA1-deficiency contributes to M2-like polarization in breast cancers, we co-cultured BP and BP + BRCA1 cells with BMDMs." (PMID 35641483, 2022). "Additionally, 53BP1 deficiency has been reported in a patient with HR restored, BRCA1-deficient breast cancer after receiving therapy of a PARPi or platinum chemotherapy." (PMID 36284291, 2022). "Hereditary breast and ovarian cancer (HBOC) caused by germline BRCA1/2 pathogenic mutations (gBRCAms) is predicted to be responsible for about 5% of breast cancers as well as the 15–18% of all ovarian cancers, and an additional 5–7% show somatic BRCA1/2 pathogenic mutations (sBRCAms)." (PMID 35267543, 2022). "However, except for the BRCA1/2 genes, there are limited studies regarding the other breast-cancer susceptibility genes, on what breast cancer type these patients are prone to, their imaging features, or histopathology characteristics." (PMID 35681739, 2022). "This suggests that diverse biological alterations underlie BRCA1-associated breast cancer risk, but a substantial fraction of this basis could be linked to BRCA1 and BRCA1-interactor profiles." (PMID 35393420, 2022). "Furthermore, the expression of ATGs, including ATG5 and ATG12, is associated with the inhibition of metastasis in breast cancer through the degradation of the neighbor to BRCA1 (NBR1) protein." (PMID 35884904, 2022). "In this work, we will review the existing experimental and epidemiological evidence implicating dysregulation of the receptor activator of nuclear factor-κB (RANK) signaling pathway in the predisposition to breast cancer among women with an inherited BRCA1 mutation." (PMID 35418083, 2022). "PARP-1 can also recruit protein MRE11, ATM (ataxiatel angiectasia mutated) to suppress the transcription factors E2F4 and P130 complexes and impact the expression of breast cancer susceptibility genes BRCA1 and RAD5, which transiently protects the DNA gaps and inhibits recombinant." (PMID 36590386, 2022). "The Basal/TN BC subtype is the most frequently found in BRCA1/2-associated breast cancer." (PMID 35884530, 2022). "To investigate whether combined EZH2/ATM inhibition induces apoptosis in BRCA1-deficient mouse mammary tumor cells, we measured the percentage of Annexin V/propidium iodide double-positive cells by flow-cytometry." (PMID 35715861, 2022).
breast cancer (continued). "The homogeneous elevation of peri-tumoural SFA could be positioned to facilitate early detection of breast cancer, particularly valuable in screening high-risk BRCA1/2 genetic mutation carriers prone to deregulation in lipid saturation." (PMID 35300617, 2022). "Whilst breast cancers arising in patients with BRCA1 or BRCA2 mutation carriers account for less than 5% of breast cancers, if epigenetic alterations, such as BRCA1 methylation are taken into account these make up approximately 15% of all patients and almost half of those with TNBC." (PMID 35158742, 2022). "Somatic mutations in BRCA1/BRCA2 have been shown to occur in 2.5% of all sporadic breast cancers." (PMID 35884530, 2022). "The lifetime risk of breast cancer in carriers of BRCA1 and BRCA2 mutations is 45–80%." (PMID 35744786, 2022). "However, there was a doubling in the risk of diabetes among BRCA1 or BRCA2 mutation carriers in the 15-year period after diagnosis of breast cancer." (PMID 35432218, 2022). "Nevertheless, whether BRCA1/2 mutations are associated with poor prognosis in breast cancer remains controversial." (PMID 35409110, 2022). "But the prevalence rate of PALB2 mutations in a non-BRCA1/2 breast cancer population specifically selected for a family history of pancreatic cancer did not appear to be significantly increased compared to that observed in other breast cancer populations." (PMID 35779338, 2022). "This has been shown by a recent study which found significantly longer survival free of invasive or distant disease when using olaparib as adjuvant therapy after neoadjuvant or adjuvant chemotherapy and local therapy in early breast cancer patients with BRCA1 or BRCA2 germline pathogenic variant." (PMID 36085046, 2022). "Inherited mutations of BRCA1 are responsible for about 40–45% of hereditary breast cancers." (PMID 35563727, 2022). "Similarly, in our simulation model patients with TN breast cancer aged under 40 years with the BRCA1 and BRCA2 pathogenic variants in stage I/II who received adjuvant chemotherapy had no survival benefit from RRBM." (PMID 36580360, 2022). "Women carrying BRCA1/2 pathogenic variants are exposed to elevated risks of developing breast cancer (BC) and are faced by a complex decision-making process on preventative measures, i.e., risk-reducing mastectomy (RRM), and intensified breast surveillance (IBS)." (PMID 36536421, 2022). "Intensive screening in BRCA1/2 mutation carriers aims to improve breast cancer (BC) prognosis." (PMID 35507134, 2022). "On the other hand, in a 2012 study of 238 high-risk breast cancer patients in Korea (including 49 BRCA1/2 PV carriers), the proportional incidence of a family history of GC did not vary between patients without BRCA1/2 PVs and BRCA1/2 PV carriers (24.7% vs. 20.5%; RR 0.947, 95% CI 0.822–1.091)." (PMID 36497436, 2022). "We then tested whether any of these genes are differentially essential for cell proliferation or survival in ovarian cancer and in breast cancer cell models that are either BRCA1 proficient or deficient." (PMID 34663427, 2021). "This is the case for women with breast cancer that also have the BRCA1 or BRCA2 mutation." (PMID 34575624, 2021). "We next determined the power of the competing RVAS tests to identify the 8 breast cancer risk genes (BRCA1-Missense, BRCA1-LoF, BRCA2-Missense, BRCA2-LoF, PALB2, BRIP1, CHEK2 and BARD1) at the three TIER levels 5%, 0.1% and 0.01% and at three levels of VE of 2%, 1% and 0.5% (Iberian: S6 Fig)." (PMID 33606672, 2021). "Clinical, molecular, and pathologic features of breast cancer in BRCA1 mutation carriers suggest the possibility that BRCA1 may function as a stem-cell regulator." (PMID 34377198, 2021).
breast cancer (continued). "Therefore, the interactions of BRCA1 mutated breast cancer cell lines with normal ADSCs were investigated in the present study." (PMID 34228231, 2021). "Higher levels of adipose tissue-derived pro-inflammatory estrogens in the setting of obesity and DNA repair deficit may thus lead to early-onset breast cancer in BRCA1/2 mutation carriers." (PMID 33649363, 2021). "In the BRCA1 gene, the c.19_47del mutation was identified in one breast cancer patient." (PMID 34490083, 2021). "Moreover, breast cancer patients with BRCA1/2 mutations show an obviously elevated risk of other or secondary malignancies." (PMID 34805171, 2021). "Therefore, newly diagnosed breast cancer patients with BRCA1/2 mutation can consider bilateral mastectomy as a treatment option regarding risk-reducing measures." (PMID 34285295, 2021). "The prevalence of BRCA1 mutations in men with breast cancer is lower; estimates range from 0 to 7%." (PMID 34461861, 2021). "Exploitation of this HR pathway has enabled the utilization of poly (ADP-ribose) polymerase (PARP) inhibitors in the drug treatment of ovarian cancers associated with germline and/or somatic BRCA1/2 PGVs and their investigation in clinical trials of advanced breast cancer." (PMID 34113003, 2021). "Family history could influence breast cancer subtypes potentially owing to the enrichment of inherited genetic mutations such as BRCA1 and BRCA2, which account for 30%–50% of the known mutations that cause breast cancer." (PMID 33737705, 2021). "Clinicopathologic characteristics associated with undergoing CPM included a family history of breast cancer, age at diagnosis of breast cancer, white race, tested for BRCA1 or BRCA2 mutation, clinical tumor stage, and lobular histology as well as patients who underwent reconstructive surgery." (PMID 33922702, 2021). "We detected nine pathogenic variants in 8 (10.66%) out of 75 selected breast cancer patients from families with hereditary breast and ovarian cancer syndrome, whose genetic tests for five BRCA1 mutations (c.5266dupC, c.181T>G, c.4035delA, c.68_69delAG, c.3700_3704delGTAAA) were negative." (PMID 33918338, 2021). "Whether patients with breast cancer who carry a BRCA1/2 variant can safely undergo breast-conserving therapy (BCT) remains controversial." (PMID 33890992, 2021). "Another study with 89% of the population with breast cancer used next-generation sequencing analysis with a 94-gene panel and showed a total of 81 pathogenic/likely pathogenic mutations in 29% of patients including mutations in BRCA1, BRCA2." (PMID 34046273, 2021). "It is speculated that the increased incidence of breast cancer in women who carry BRCA1, BRCA2 or PALB2 germline mutations is due to deficiencies in DNA damage repair." (PMID 35187501, 2021). "A functional HR assay, the recombination Repair CAPacity (RECAP) test, was originally developed to identify HRD in breast cancers and more recently ovarian cancers, detecting both BRCA1/2-deficient and BRCA1/2-proficient HRD tumours in ex vivo tumour slice cultures." (PMID 34283069, 2021). "Furthermore, Hyaluronan Mediated Motility Receptor (HMMR), a low penetrance breast cancer susceptibility gene important for regulating apicobasal polarity, is upregulated in BRCA1-deficient tumors." (PMID 35008272, 2021). "This incidence was much lower than that reported in Chinese HBOC, in which 5.74 % of breast cancer and 21.79 % of ovarian cancer patients had BRCA1/2 germline mutations, with an overall pathogenic mutation frequency of 69.9 % and 71.1 % for BRCA1 and BRCA2 exons, respectively." (PMID 33563323, 2021). "An ongoing phase 1/2 study of olaparib and the PD-L1 inhibitor durvalumab in breast cancer patients with BRCA1/2 mutations demonstrated that 24 of 30 patients who were eligible for trial entry by study design achieved durable and adaptable cancer control at 12 weeks of combination therapy." (PMID 34552581, 2021).